JUN (Jun proto-oncogene, AP-1 transcription factor subunit)
Diseases named in the same sentence as JUN in open-access papers (continued):
Sharing a sentence is not in itself a finding about the gene and the disease.
Burkitt lymphoma (3 papers, 2020 to 2024). A rare form of malignant mature B-cell non-Hodgkin lymphoma. "In the context of Burkitt’s lymphoma, JUN remains a crucial protein for andrographolide, potentially serving as a marker protein for the therapeutic application of andrographolide in treating Burkitt’s lymphoma." (PMID 38148335, 2024). "To verify the molecular mechanism of andrographolide inhibits Burkitt’s lymphoma, we examined JUN and CASP3 protein expression in andrographolide treated Burkitt’s lymphoma by IF." (PMID 38148335, 2024). "This study discovered that andrographolide inhibited the progression of Burkitt’s lymphoma by interacting with JUN and CASP3 proteins." (PMID 38148335, 2024). "Andrographolide inhibits the growth of Burkitt’s lymphoma by inhibiting JUN and CASP3 proteins." (PMID 38148335, 2024). "The results showed that andrographolide increased JUN and CASP3 protein expression in Burkitt’s lymphoma PDX." (PMID 38148335, 2024). "We observed that JUN and CASP3 expression were lower in Burkitt lymphoma instances where andrographolide inhibition was weak compared to those with strong inhibition." (PMID 38148335, 2024). "Moreover, we observed a increased in the expression of JUN (c-Jun) and CASP3 (Caspase 3) proteins in Burkitt’s lymphoma cells treated with andrographolide." (PMID 38148335, 2024). "Thus, JUN and CASP3 expression might be employed as predictive markers for andrographolide in the treatment of Burkitt’s lymphoma." (PMID 38148335, 2024).
erythroleukemia (3 papers, 2019 to 2024). Acute erythroid leukemia characterised by the presence of at least 50% erythroid precursors and at least 20% myeloblasts in the bone marrow. "Shaulian and Karin (2001) found that cell proliferation and cell cycle were inhibited in mouse fibroblasts and erythroleukemia cell lines when the expressions of FOS and JUN were suppressed by antisense RNA." (PMID 34199615, 2021).
fibrosis (3 papers, 2020 to 2023). the formation of excess fibrous connective tissue in an organ or tissue in a reparative or reactive process. "In accordance with our results from the human fibroblasts on the hydrogel, a possibility is that bleomycin first leads to a temporary fibrosis and stiffening of the skin that then leads to JUN activation." (PMID 32814713, 2020). "In conclusion, these data demonstrate that JUN leads to dermal fibrosis through the distinct activation of hedgehog signaling in CD26+ fibroblasts." (PMID 32814713, 2020).
hypertrophic cardiomyopathy (3 papers, 2022 to 2025). A condition in which the myocardium is hypertrophied without an obvious cause. "JUN is enriched in hypertrophic cardiomyopathy, MAPK signaling, and VEGF pathways, indicating its integration of cellular stress responses and growth signaling." (PMID 41465087, 2025).
hyperuricemia (3 papers, 2022 to 2023). An abnormally high level of uric acid. "Further research confirmed that CCE has the potential to regulate the mRNA expression of ADA, PNP, and JUN in the kidney, thereby alleviating hyperuricemia associated with anti-inflammatory activity." (PMID 38026974, 2023). "We conclude that CCE has anti-hyperuricemia effects and alleviates renal inflammation in a rat model of hyperuricemia, and these efficacies are associated with the reversal of increased ADA, PNP, and JUN mRNA expression in renal tissues." (PMID 38026974, 2023).
idiopathic pulmonary fibrosis (3 papers, 2022 to 2024). Idiopathic pulmonary fibrosis (IPF) is a nonneoplastic pulmonary disease that is characterized by the formation of scar tissue within the lungs in the absence of any known cause. "Nuclear expression of c-JUN was documented in a fibroblast subset obtained from diverse fibrotic end-stage diseases, including idiopathic pulmonary fibrosis (IPF), scleroderma, myelofibrosis, kidney, pancreas and heart-fibrosis." (PMID 35269565, 2022).
IgA nephropathy (3 papers, 2016 to 2022). "By overlap, we found three genes, JUN, FOS, and PLAU were simultaneously participated in aging and inflammation, and were also previously reported to be related to IgA nephropathy." (PMID 27127888, 2016). "Only PLAU, JUN, and FOS were related to DNA damage, telomere dysfunction-induced aging markers, neutrophil function and IgA nephropathy." (PMID 27127888, 2016).
influenza (3 papers, 2020 to 2024). An acute viral infection of the respiratory tract, occurring in isolated cases, in epidemics, or in pandemics; it is caused by serologically different strains of viruses (influenzaviruses) designated A, B, and C, has a 3-day incubation period, and usually lasts for 3 to 10 days. "With the merger of PPI network, we have identified a core network, including TNF, IL-6, IL-1B, JUN, and MAPK1, as crucial targets of the anti-influenza efficacy of TFA." (PMID 35123452, 2022). "The analysis using CytoHubba, TNF, IL10, IL-6, IL-1B, JUN, and MAPK1 was found to have the highest average scores and identified as crucial targets for the anti-influenza efficacy of TFA." (PMID 35123452, 2022).
intestinal tumor (3 papers, 2015 to 2022). "JUN autoregulates its own transcription via enhancer elements in its promoter and forms a complex with β-catenin and TCF4 to activate JUN transcription in a JNK-dependent manner during mouse intestinal tumor formation." (PMID 26134322, 2015).
kidney damage (3 papers, 2020 to 2025).
laryngeal carcinoma (3 papers, 2013 to 2024). Carcinoma that arises from the laryngeal epithelium. "Que YH postulated that JUN gene overexpression and the c-Jun protein’s imbalance of cell proliferation and differentiation could contribute to laryngeal cancer." (PMID 38032489, 2024).
lentivirus infection (3 papers, 2009 to 2021). Virus diseases caused by the Lentivirus genus. "Therefore, we overexpressed FOS and JUN in HASMCs via lentivirus infection." (PMID 34485398, 2021).
malignant glioma (3 papers, 2015 to 2023). A grade III or grade IV glioma arising from the central nervous system. "Expression of genes coding for GBM-specific TFs was higher in malignant gliomas as is exemplified by the expression of HOX genes, JUN and TWIST, in an agreement with previous reports." (PMID 36850002, 2023). "A possible link has been suggested between c-JUN and c-FOS expression and IL-13Rα2, which is consistent with the expression profile of human IL-13 Rα2 in malignant gliomas." (PMID 36830725, 2023).
meningioma (3 papers, 2007 to 2016). A generally slow growing tumor attached to the dura mater. "In line with the microarray data, the PCR data showed a decrease in the median expression level of BMP4, SMAD9, JUN, RUNX2 and an increase in the median expression level of FKBP1A in Grade 3 meningiomas when compared to Grade 1 meningiomas." (PMID 17937814, 2007). "Considering inconsistent expression of SOS2/KRAS and JUN/FOS in fibroblastic meningioma, we speculated that activated Ras promoted tumor growth through the PI3K/Akt pathway, but not via ERK-c-Jun/c-Fos pathway." (PMID 23285163, 2012).
myopia (3 papers, 2013 to 2025). "Therefore, we selected EGR1, FOS, JUN, VIP and VIPR2 as functional candidates and investigated their potential association with high myopia." (PMID 23637909, 2013). "EGR1, JUN, FOS and VIP are unlikely to be important in predisposing humans to high myopia." (PMID 23637909, 2013).
pancreatic adenocarcinoma (3 papers, 2016 to 2025). "Conversely, the expression levels of CCND1, DUSP2, ETS2, JUN, and RALGDS were decreased in lung and pancreatic adenocarcinomas with KRAS mutations." (PMID 33982211, 2021).
papillary thyroid carcinoma (3 papers, 2021 to 2025). "Specifically, noteworthy are our findings regarding the potential diagnostic value of CCNA1 and SFN genes in papillary thyroid carcinoma, while the reduced expression of CDKN1C, FOS, and JUN genes in follicular carcinoma suggests their value in distinguishing the thyroid pathologies." (PMID 40722651, 2025).
tauopathy (3 papers, 2020 to 2024). Neurodegenerative disorders involving deposition of abnormal tau protein isoforms (tau proteins) in neurons and glial cells in the brain. "In addition, the RELA and JUN TFs link back to protein homeostasis pathways (i.e., ‘ubiquitin protein ligase binding’), which is reflected in the gradual accessibility increments of tauopathy- and degradation system-associated genes (online resource)." (PMID 35976433, 2022). "Together, we conclude that tauopathy astrocytes show signs of a JUN(B)-mediated pro-inflammatory state, while TAs in PSP additionally display a TFEB-mediated downregulation of lysosomal degradation." (PMID 35976433, 2022). "Thus, to discriminate the two tauopathies, we hereby propose JUN(B,D)HIGH, FOS(L1,L2)HIGH as well as the involvement of DUX4, KLF5, MAX::MYC, PAX6, and PPARG to support the identity of CBD-originated astrocytes." (PMID 35976433, 2022). "In a subsequent step, overall feature importance assessment highlighted IER- and cellular immunity-related TFs (FOS, JUN, NFATC2/3, STAT1) as most useful in predicting the tauopathy or Ctrl state." (PMID 35976433, 2022). "Immunohistochemical analysis in postmortem brain tissue of individuals with the very rare 3R tauopathy Pick's disease revealed colocalization of AP-1 components such as FOS, JUN, and MYC with the disease-defining intraneuronal pTau deposits (Pick bodies) and neuronal cytoplasms." (PMID 35976433, 2022).
thymic epithelial tumors (3 papers, 2012 to 2014). "We found that the common up-regulated TF in both cell lines is JUN, a protoncogene that plays a dual role in regulation of tumor cell proliferation, and recently reported as candidate biomarker for personalized therapy in thymic epithelial tumors." (PMID 25077705, 2014).
thymoma (3 papers, 2012 to 2023). A neoplasm arising from the epithelial cells of the thymus. "Only in thymomas and GBMs, JUN was significantly overexpressed in tumors when compared to adjacent normal tissue." (PMID 36850002, 2023). "Only in thymoma (THYM) and GBM, JUN expression was increased as compared to normal adjacent tissues." (PMID 36850002, 2023).
tuberculosis (3 papers, 2020 to 2024). A chronic, recurrent infection caused by the bacterium Mycobacterium tuberculosis. "Activation of STAT1 and c-JUN is a possible mechanism in macrophages for patients to survive against active tuberculosis." (PMID 32290250, 2020).
ulcerative colitis (3 papers, 2022 to 2025). An inflammatory bowel disease involving the mucosal surface of the large intestine and rectum. "JUN, Akt1, and MAPK1 were identified as the “hub targets” involved in the effects of Modified Sanmiaosan on ulcerative colitis." (PMID 35966251, 2022). "The findings indicated that FS could modulate the progression of ulcerative colitis via multiple targets, with STAT3, EGFR, ESR1, PTGS2, NF-κB1 and JUN identified as the six key targets significantly involved in the pathogenesis and progression of ulcerative colitis." (PMID 40649400, 2025).
avian influenza (2 papers, 2013 to 2022). Infection of domestic and wild fowl and other birds with influenza A virus. "After the analysis of DEGs and hub genes, a total of three genes, namely EGR1, JUN and FOS, were screened, which have been reported to have a major role in the resistance of chickens to avian influenza." (PMID 36557693, 2022). "Recently, JUN has been demonstrated to be differentially regulated, and specifically down-regulated during LPAIV infection, in a gene expression study of avian influenza infected lung cell lines." (PMID 23521892, 2013).
chronic obstructive pulmonary disease (2 papers, 2017 to 2022). A chronic and progressive lung disorder characterized by the loss of elasticity of the bronchial tree and the air sacs, destruction of the air sacs wall, thickening of the bronchial wall, and mucous accumulation in the bronchial tree. "A total of 379 targets related to BHC and 7391 targets related to COPD were obtained, including 313 potential targets of BHC in treating chronic obstructive pulmonary disease, with JUN, AKT1, TNF, IL6, EGFR, MAPK1, and MAPK14 as the core targets." (PMID 36523421, 2022).
coronary disease (2 papers, 2019 to 2025). "Heterozygosity at coronary disease causal variation, or genome editing of these variants, is associated with decreased binding of both JUN and TCF21 and loss of expression in cis, supporting a transcriptional mechanism for disease risk." (PMID 31014396, 2019). "We show here that TCF21 and JUN regulate expression of two presumptive causal coronary disease genes, SMAD3 and CDKN2B-AS1, in part by interactions with histone deacetylases and acetyltransferases." (PMID 31014396, 2019).
cutaneous melanoma (2 papers, 2019 to 2022). A primary melanoma arising from atypical melanocytes in the skin. "TNFα can also activate ATF4 and JUN, resulting in dedifferentiated cutaneous melanoma cells." (PMID 35682684, 2022). "In contrast, ATF4 (activating transcription factor 4), and JUN, which both integrate stress signals, repress MITF expression and trigger cutaneous melanoma cell dedifferentiation." (PMID 35682684, 2022).
dry eye (2 papers, 2024). "Increased transcriptional activity of FOS, JUN and ELK have been previously linked to activation of IL1b signaling, further implicating this pathway as a key driver of keratocyte inflammation in dry eye." (PMID 39677756, 2024). "JUN and MAPK8 can affect the symptoms of xerostomia and xerophthalmia in SS patients by regulating the expression of AQP5." (PMID 38728503, 2024).
esophageal adenocarcinoma (2 papers, 2021 to 2025). A malignant tumor with glandular differentiation arising predominantly from Barrett mucosa in the lower third of the esophagus. "However, further prospective and biomolecular studies are necessary to confirm that JUN-positive tumors represent a high-risk subgroup with low responsiveness to neoadjuvant treatment in esophageal adenocarcinoma." (PMID 40701988, 2025).
Follicular Thyroid Carcinoma (2 papers, 2015 to 2025). "Our current study’s findings are consistent with our previous research, further substantiating that the FOS and JUN genes serve as potential molecular markers for diagnosing thyroid malignancies, particularly follicular thyroid carcinoma (FTC)." (PMID 40722651, 2025).
HIV-1 infection (2 papers, 2024 to 2025). The type species of lentivirus and the etiologic agent of acquired immunodeficiency syndrome (AIDS). "In the gene-pathway connections, multiple molecules and kinases for NF-κB signaling (e.g., IKBKB, JUN, FOS, MAP2K2, NFKBIA, TLR4) connected the HIV-1 infection and other inflammatory or anti-viral pathways." (PMID 39283947, 2024).
insomnia (2 papers, 2021 to 2024). A sleep disorder characterized by difficulty in falling asleep and/or remaining asleep. "A transcription factor (TF)–target analysis of the TRRUST database reveals that numerous targets are regulated by TFs such as NFKB1, RELA, SP1, JUN, and others, suggesting that these TFs may play an important role in insomnia." (PMID 38927034, 2024).
keloid (2 papers, 2021 to 2022). An irregularly shaped, elevated mark on the skin caused by deposits of excessive amounts of collagen during wound healing. "We identified four subpopulations of endothelial cells in keloid and normal scar tissue by scRNA-seq data: MMP1+ Endo0, FOS + JUN + Endo1, IL6+CSF3+ Endo2, CXCL12 Endo3." (PMID 36082167, 2022).
laryngeal squamous cell carcinoma (2 papers, 2022 to 2024). A squamous cell carcinoma that arises from the larynx. "Overexpression of JUN is detected in patients with laryngeal squamous cell carcinoma and could be related to progression due to its overactivation with c-Fos." (PMID 39409043, 2024).
latent infection (2 papers, 2008 to 2025). "Notably, JUN functions at multiple stages of HSV-1 latent infection to promote reactivation, a mechanism that may be relevant to HIV latency." (PMID 40574839, 2025).
leiomyoma (2 papers, 2007 to 2020). A well-circumscribed benign smooth muscle neoplasm characterized by the presence of spindle cells with cigar-shaped nuclei, interlacing fascicles, and a whorled pattern. "Although all JUN and FOS family genes are down-regulated in uterine fibroids, it is unclear if the loss in expression of all AP-1 genes is necessary to cause the enhancer defects observed in leiomyoma cells." (PMID 32094355, 2020). "They included several genes such as NR2F1, PNN, Smad4, Smad5, STAT5B, JUN, TGIF2, and ATF1 that were over-expressed while RUNX3, STAT1, STAT6, EGR3, GAS7, Smad1, and EDF1 were underexpressed in leiomyomas as compared to keloid/incisional scars." (PMID 17718906, 2007). "Notably, expression of the JUN, FOS, and ATF families of genes was down-regulated in leiomyoma tissue." (PMID 32094355, 2020).
leishmaniasis (2 papers, 2024). Infectious disease that is transmitted through the bite of hematophagous female phlebotomine sand flies. "The identification of hub genes of recruited datasets suggested that TNF, SOCS3, JUN, TNFAIP3, and CXCL9 may serve as potential infection biomarkers and could deserve value as prognostic biomarkers for leishmaniasis." (PMID 38839916, 2024).
lung diseases (2 papers, 2020 to 2024). "Among the over-represented TFs in PETGenes, NF-KB1, CREB, STAT, FOS, and JUN, have been reported to play a critical role in regulating inflammation in lung diseases, and we extracted their TFBS in the promoter region of their target genes." (PMID 33643286, 2020).
lymphocytic leukemia (2 papers, 2014 to 2020). "c-JUN was reported to promotes BCR-ABL induced lymphoid leukemia." (PMID 24466173, 2014).
myocardial inflammation (2 papers, 2022 to 2025). "Considering that monocytes in acute myocarditis show altered JUN/FOS activity, along with changes in the metabolism-related gene pathway, further investigation is required to determine whether monocytes in acute myocarditis resemble monocyte-derived macrophages activated without prior priming." (PMID 36225942, 2022). "Thus, in contrast to JUN and FOS down-regulated at the time of myocarditis, metabolism-related genes were significantly up-regulated." (PMID 36225942, 2022). "In addition, genes involved in the regulatory network of JUN and FOS were mostly downregulated during myocarditis in classical monocytes." (PMID 36225942, 2022).
ovarian tumor (2 papers, 2022 to 2025). "In OC, KRAS was downregulated, whereas the other hub genes CTNNB1, BRCA1, and JUN were upregulated in ovarian tumor tissues." (PMID 41186627, 2025).
papilloma (2 papers, 2011 to 2020). A benign epithelial neoplasm that projects above the surrounding epithelial surface and consists of villous or arborescent outgrowths of fibrovascular stroma. "Inhibiting c-JUN activity in basal keratinocytes blocks chemically induced papilloma formation because of the lack of expression of the AP-1 target genes." (PMID 21789792, 2011).